POLR3A (RNA polymerase III subunit A)
Description:
Catalytic core component of RNA polymerase III (Pol III), a DNA-dependent RNA polymerase which synthesizes small non-coding RNAs using the four ribonucleoside triphosphates as substrates. Synthesizes 5S rRNA, snRNAs, tRNAs and miRNAs from at least 500 distinct genomic loci. Pol III-mediated transcription cycle proceeds through transcription initiation, transcription elongation and transcription termination stages. During transcription initiation, Pol III is recruited to DNA promoters type I, II or III with the help of general transcription factors and other specific initiation factors. Once the polymerase has escaped from the promoter it enters the elongation phase during which RNA is actively polymerized, based on complementarity with the template DNA strand. Transcription termination involves the release of the RNA transcript and polymerase from the DNA. Forms Pol III active center together with the second largest subunit POLR3B/RPC2. Appends one nucleotide at a time to the 3' end of the nascent RNA, with POLR3A/RPC1 contributing a Mg(2+)-coordinating DxDGD motif, and POLR3B/RPC2 participating in the coordination of a second Mg(2+) ion and providing lysine residues believed to facilitate Watson-Crick base pairing between the incoming nucleotide and template base. Typically, Mg(2+) ions direct a 5' nucleoside triphosphate to form a phosphodiester bond with the 3' hydroxyl of the preceding nucleotide of the nascent RNA, with the elimination of pyrophosphate. Pol III plays a key role in sensing and limiting infection by intracellular bacteria and DNA viruses. Acts as a nuclear and cytosolic DNA sensor involved in innate immune response. Can sense non-self dsDNA that serves as template for transcription into dsRNA. The non-self RNA polymerase III transcripts, such as Epstein-Barr virus-encoded RNAs (EBERs) induce type I interferon and NF-kappa-B through the RIG-I pathway.
Synonyms: RPC155; RPC1; hRPC155; C160; ADDH; HLD7; WDRTS
Tractability: Small molecule: a drug acting on it is in phase 2 or 3 trials; a structure with a bound ligand is known. PROTAC: ubiquitination databases record sites on it; its protein half-life has been measured.
Target class: Enzyme; Transferase
Gene: Protein-coding gene on chromosome 10 (77,953,148 to 78,029,549, reverse strand). Ensembl gene ENSG00000148606.
Subcellular location: Nucleus; Cytoplasm, cytosol
Subcellular location (Human Protein Atlas): Nucleoplasm
Pathways (Reactome):
Gene expression (Transcription): RNA Polymerase III Abortive And Retractive Initiation; RNA Polymerase III Chain Elongation; RNA Polymerase III Transcription Initiation From Type 1 Promoter; RNA Polymerase III Transcription Initiation From Type 2 Promoter; RNA Polymerase III Transcription Initiation From Type 3 Promoter; RNA Polymerase III Transcription Termination
Immune System: Cytosolic sensors of pathogen-associated DNA
Gene Ontology:
Molecular function: 5'-3' RNA polymerase activity; DNA-directed RNA polymerase activity; DNA/RNA hybrid binding; magnesium ion binding; protein binding; zinc ion binding; chromatin binding; DNA binding
Biological process: innate immune response; positive regulation of interferon-beta production; termination of RNA polymerase III transcription; transcription by RNA polymerase III; transcription initiation at RNA polymerase III promoter; tRNA transcription by RNA polymerase III; DNA-templated transcription; DNA-templated transcription termination
Cellular component: cytoplasm; membrane; nucleoplasm; nucleus; RNA polymerase III complex; cytosol
Genetic constraint (gnomAD): Loss-of-function variants: 93 observed, 132.18 expected, observed/expected ratio (o/e) 0.7, 90% interval 0.59 to 0.84. The upper end of that interval is the gene's LOEUF score, 0.84, which puts it in group 3 of 6, group 1 being the genes least tolerant of losing a copy. Missense variants: 1,236 observed, 1,644.5 expected, observed/expected ratio (o/e) 0.75, 90% interval 0.72 to 0.79. Synonymous variants: 554 observed, 622.03 expected, observed/expected ratio (o/e) 0.89, 90% interval 0.83 to 0.95.
Gene-disease validity (ClinGen):
ClinGen rates the evidence that POLR3A causes each of these diseases.
POLR3A-related disorder (autosomal recessive): Definitive. Disorder in which the cause of disease is a variation in the POLR3A gene.
Homologues: Orthologues: chimpanzee POLR3A (99% identical), macaque POLR3A (99% identical), dog POLR3A (99% identical), pig POLR3A (98% identical), rabbit POLR3A (98% identical), mouse Polr3a (98% identical), rat Polr3a (98% identical), guinea pig POLR3A (97% identical), tropical clawed frog polr3a (92% identical), zebrafish polr3a (90% identical), Caenorhabditis elegans rpc-1 (57% identical), Drosophila melanogaster Polr3A (57% identical). Paralogues in human: POLR2A (36% identical), POLR1A (30% identical).
Diseases named in the same sentence as POLR3A in open-access papers:
POLR3A is named in the same sentence as 85 diseases in open-access papers, as found by Europe PMC text mining. Sharing a sentence is not in itself a finding about the gene and the disease. The quoted sentences say what the papers report.
leukodystrophy (46 papers, 2015 to 2024). Leukodystrophies are a group of rare, progressive, metabolic, genetic diseases that affect the brain, spinal cord and often the peripheral nerves. "While biallelic POLR3A loss‐of‐function variants are traditionally linked to hypomyelinating leukodystrophy, patients with a specific splice variant c.1909+22G>A manifest as adolescent‐onset spastic ataxia without overt leukodystrophy." (PMID 38700104, 2024). "POLR3A variants are recognized to be associated with a phenotype known as 4H‐leukodystrophy which stands for hypomyelination, hypodontia, and hypogonadotropic hypogonadism." (PMID 39436788, 2024). "In the last few years, our group has identified and validated eight genes causative for leukodystrophy, including POLR3A, POLR3B, POLR1C, POLR3D, EPRS1, VARS1, and ABHD16A." (PMID 39062571, 2024). "This study aimed to investigate the clinical, radiological, and genetic features of POLR3-related leukodystrophy caused by mutations in POLR3A or POLR1C." (PMID 38550343, 2024). "Two of these patients showed heterozygosity variants in the POLR3A gene, already described in the literature as causing leukodystrophy." (PMID 36140376, 2022). "These leukodystrophies result from a number of biallelic pathogenic variants in POLR3A, POLR3B, POLR1C, and POLR3K, which encode individual subunits of the RNA polymerase III (Pol III) complex." (PMID 34753215, 2022). "Recently, a multicenter retrospective study including 150 patients with 4H leukodystrophy demonstrated that 56 (37.3%) patients carried the mutations in POLR3A, 81 (54%) in POLR3B, and 13 (8.7%) in POLR1C." (PMID 36042647, 2022). "In one of these patients, we identified variants in compound heterozygosity in the POLR3A gene already described in the literature, as causing leukodystrophy." (PMID 36140376, 2022). "More than 140 POLR3A (NM_007055.3) missense mutations are related to the pathogenesis of POLR3-related leukodystrophy and spastic ataxia." (PMID 36140376, 2022). "To date, more than 140 POLR3A (NM_007055.3) missense mutations are related to the pathogenesis of POLR3-related leukodystrophy and spastic ataxia." (PMID 36140376, 2022). "POLR3A or POLR3B mutations cause the majority of POLR3-related leukodystrophy cases, with POLR1C mutations accounting for approximately 5% of cases." (PMID 35685919, 2022). "Biallelic mutations in POLR3A have been associated with childhood‐onset hypomyelinating leukodystrophies and adolescent‐to‐adult‐onset spastic ataxia, the latter of which has been linked to the intronic variant c.1909 + 22G>A." (PMID 34753215, 2022). "4H leukodystrophy has been found to be caused by biallelic pathogenic variants in POLR3A, POLR3B, POLR1C, and POLR3K, each of which encode subunits of the POLR3 complex." (PMID 33005949, 2021). "Here, we report a 41-year-old woman of POLR3-related leukodystrophy by carrying compound heterozygous pathogenic variants of c.2554A>G (p.M852V) and c.2668G>T (p.V890F) in the POLR3A gene." (PMID 33716926, 2021). "A total of 150 patients with 4H leukodystrophy and pathogenic variants in POLR3A, POLR3B, or POLR1C were included." (PMID 33005949, 2021). "About the clinical aspect, the neurological presentation of our patients is peculiar, since it differs from classic leukodystrophy, hereditary spastic ataxia, or extrapyramidal syndrome associated with POLR3A gene mutations." (PMID 33085208, 2020). "Biallelic variants in POLR3A cause 4H leukodystrophy, characterized by hypomyelination in combination with cerebellar and pyramidal signs and variable non-neurological manifestations." (PMID 31940116, 2020). "Clinical and MRI findings in patients with a striatal variant of POLR3A-related disease are distinct from 4H leukodystrophy and associated with one of two intronic variants, c.1771-6C > G or c.1771-7C > G, in combination with another POLR3A variant." (PMID 31940116, 2020).
leukodystrophy (continued). "Patient 5, in addition to CHH, also developed a mild hypomyelinating leukodystrophy phenotype, which is likely associated with the heterozygous condition found in the POLR3A gene." (PMID 32982993, 2020). "Mutations POLR3A were first linked to young onset of hypomyelination, hypodontia and hypogonadotropic hypogonadism (4H leukodystrophy)." (PMID 33085208, 2020). "Thinning of corpus callosum, another common feature of 4H leukodystrophy, though somewhat less common in patients with carrying POLR3A variants, was only present in one of the nine patients with the striatal variant." (PMID 31940116, 2020). "Although our study is limited by the relatively small number of patients, clinical manifestation and MRI differ from 4H leukodystrophy and are consistent with a distinct, striatal variant of POLR3A-related disease." (PMID 31940116, 2020). "POLR3-related leukodystrophy is caused by biallelic mutations in POLR3A, POLR3B, POLR1C, and POLR3K (through interaction with POLR3B) genes." (PMID 31438894, 2019). "Altogether, these results provide the first evidence that a leukodystrophy-causing POLR3A mutation causes a global reduction in transcription levels of nuclear-encoded tRNA genes." (PMID 30898877, 2019). "Collectively, we identified novel compound heterozygous mutations of the POLR3A gene that caused POLR3-related leukodystrophy in the patient combined with the clinical presentation, MRI brain pattern, and medical exome sequencing." (PMID 31438894, 2019). "Most published mutations of POLR3A associated with POLR3-related leukodystrophy have focused on mutations that cause a change of amino acid; studies of splice site mutations and copy number variants are rare." (PMID 31438894, 2019). "4H syndrome is a rare congenital hypomyelinating leukodystrophy inherited as an autosomal recessive disorder due to mutations in the POLR3A and POLR3B gene." (PMID 29618326, 2018). "Pol III-related leukodystrophies are inherited in an autosomal recessive manner and result from mutations in POLR3A gene on chromosome 10q22 or the POLR3B genes on chromosome 12q23." (PMID 29618326, 2018). "Recessive mutations in the ubiquitously expressed POLR3A gene cause one of the most frequent forms of childhood-onset hypomyelinating leukodystrophy (HLD): POLR3-HLD." (PMID 28407788, 2017). "No Tunisian studies have been published about POLIII‐related leukodystrophy due to POLR3A variants." (PMID 39436788, 2024). "Herein, in a cohort of five families from Sicily (Italy), we detected two cases of patients affected by POLR3-related leukodystrophy, one due to a compound heterozygous mutation in the POLR3A gene, including a previously undescribed missense mutation (c.328A > G (p.Lys110Glu))." (PMID 36140376, 2022). "Other than severe childhood-onset hypomyelinating leukodystrophy, variants in POLR3A have been associated with milder, late-onset gait disorders with central hypomyelination, and with parkinsonism dystonia with basal ganglia involvement, with or without non-neurological signs." (PMID 34296356, 2022). "Finally, whole‐exome sequencing (WES) was performed in January 2019 which was reported as follows: compound heterozygote mutation in POLR3A gene (intron 13: c.1771‐6C > G, exon 31: c.4037G > A p.C1346Y) related to 4H leukodystrophy." (PMID 36397839, 2022). "4H or POLR3-related leukodystrophy is an autosomal recessive disorder typically characterized by hypomyelination, hypodontia, and hypogonadotropic hypogonadism, caused by biallelic pathogenic variants in POLR3A, POLR3B, POLR1C, and POLR3K." (PMID 33005949, 2021). "The existence of mild and overlapping hypomyelinating leukodystrophy phenotypes could be attributed to heterozygous variants found in the POLR3A gene as a result of an abnormal enzymatic function of the RNA Pol III catalytic subunit." (PMID 32982993, 2020).
leukodystrophy (continued). "These are the first reports of long deletions causing POLR3-related leukodystrophy, suggesting that deletions and duplications in POLR3A or POLR3B should be investigated in patients with a compatible phenotype, especially if one pathogenic variant has been identified." (PMID 26045207, 2015). "Recessive mutations in the POLR3A gene cause POLR3-HLD (the second-most-common form of childhood-onset hypomyelinating leukodystrophy—MIM #607694, #614381 #616494), a type of neurodegenerative disorder featured by deficient cerebral myelin formation." (PMID 36140376, 2022). "Recessive mutations in the POLR3A gene cause POLR3-HLD (the second-most-common form of childhood-onset hypomyelinating leukodystrophy), a neurodegenerative disorder featuring deficient cerebral myelin formation." (PMID 36140376, 2022). "Screening of this variant by PCR‐sequencing in the two remaining patients confirmed the diagnosis of POLR3A‐related leukodystrophy." (PMID 39436788, 2024). "In the present study, all patients with confirmed POLR3A‐related leukodystrophy displayed a similar clinical phenotype and carried the same homozygous variant, indicating a potential founder effect." (PMID 39436788, 2024). "While dystonia and tremor are common symptoms in patients with POLR3A‐related hypomyelinating leukodystrophy, they are often under‐recognised." (PMID 38700104, 2024). "To date, only one patient with POLR3A‐related leukodystrophy and parkinsonism was reported to have response to pallidal nucleus DBS." (PMID 38700104, 2024). "The aim of this study was to contribute to the clinical, radiological, and genetic characterization of POLR3A‐related leukodystrophy in a Tunisian cohort." (PMID 39436788, 2024). "In the present study, we identified a total of six unrelated Tunisian families with confirmed POLR3A‐related leukodystrophy." (PMID 39436788, 2024). "We report six cases of genetically confirmed POLR3A‐related leukodystrophy belonging to six unrelated Tunisian families, along with a review of previously published pediatric cases." (PMID 39436788, 2024). "POLR3-related leukodystrophy is caused by biallelic pathogenic variants in genes encoding subunits of Pol III, i.e. POLR3A, POLR3B, POLR1C and POLR3K." (PMID 36451185, 2022). "We demonstrate the clinicopathologic description of POLR3A‐related neurodegenerative disease and also mention the differential diagnosis of the childhood‐onset hypomyelinating leukodystrophy and late‐onset spastic ataxia phenotypes." (PMID 34753215, 2022). "Recessive mutations in POLR3A, encoding the largest subunit of Pol III, cause POLR3-related hypomyelinating leukodystrophy (POLR3–HLD), characterized by deficient central nervous system myelination." (PMID 30898877, 2019). "Mutations in POLR3A and RARS were first identified in Chinese patients with Pol III-related leukodystrophy and hypomyelinating leukodystrophy, respectively." (PMID 29451896, 2018). "Mutations in POLR3A and POLR3B, which encode the two largest subunits of RNA polymerase III (Pol III), have now been identified in several patients with 4H leukodystrophy." (PMID 26113998, 2015). "It belongs to a spectrum of clinically and radiologically overlapping diseases caused by recessive mutations in either POLR3A or POLR3B, and collectively designated as “Pol III-related leukodystrophies”." (PMID 25868523, 2015). "The patient was firstly diagnosed as an undefined hypomyelination leukodystrophy and reached the final genetically confirmed diagnosis ten years later, following the description of POLR3A and POLR3B as disease genes." (PMID 26204956, 2015). "Demographic, clinical, and genetic findings in our patients with POLR3A‐related leukodystrophy." (PMID 39436788, 2024).